PALB2 (partner and localizer of BRCA2)
Diseases named in the same sentence as PALB2 in open-access papers (continued):
Sharing a sentence is not in itself a finding about the gene and the disease.
breast cancer (continued). "For missense variants in aggregate, rare missense variants in specific domains in BRCA1, ATM, CHEK2, and PALB2 were significantly associated with increased risk of certain breast cancer subtypes." (PMID 37790698, 2023). "Mutations in the PALB2 gene have been associated with increased cancer risk, notably for breast cancer; however, the importance of its expression has been poorly explored." (PMID 37372450, 2023). "In this review we have highlighted that BRCA and PALB2 genes are major contributors in breast cancer predisposition in black African women and Caucasian." (PMID 38192440, 2023). "In 2020, modified segregation analyses performed in 524 breast cancer families with pathogenic variants in PALB2 confirmed that this gene confers a risk for breast cancer that is comparable to that of BRCA2." (PMID 37444426, 2023). "In our previous large study, two PALB2 founder mutations (c.509_510delGA and c.172_175delTTGT) were associated with a 4.5-fold increased risk of breast cancer." (PMID 37510234, 2023). "PALB2 mutations confer about a 5-fold increase in the risk of breast cancer and about a 3-fold increase in the risk of ovarian cancer." (PMID 37510234, 2023). "In our study cohorts, the OR for breast cancer risk in women with PALB2 P/LP variants was between 8.1 and 9.3 in breast cancer patients compared to non-HBOC cancer patients and non-cancer population, respectively." (PMID 37686625, 2023). "One multi-national study that analyzed data from 524 families with PALB2 PVs in 21 countries concluded that the estimated relative risk (RR) of breast cancer was 7.18 (95% CI, 5.82- 8.85; p=6.5×10-76)." (PMID 37781190, 2023). "The more precise interrelation between these manifestations and PALB2 P/LP variants should be further investigated on a larger, independent breast cancer cohort." (PMID 37686625, 2023). "Germline PALB2 mutation is estimated to be present in about 1% of breast cancer patient populations and is known for its remarkable increased risk of breast cancer and pancreatic cancer." (PMID 38098088, 2023). "PALB2 is the third most important breast cancer susceptibility gene after BRCA1 and BRCA2, presenting with varying prevalence and mutational profiles in different populations." (PMID 37686625, 2023). "This highlights the growing importance of BRCA1/2 and PALB2 alterations in breast cancer susceptibility risk and the treatment of index patients." (PMID 38098088, 2023). "The same study reported that the cumulative breast cancer risk among PALB2 mutation carriers was 14% (95% CI: 9–20) by 50 years of age." (PMID 36980802, 2023). "PALB2 is a thoroughly studied predisposition gene in breast cancer, and almost all truncating variants are damaging." (PMID 37610374, 2023). "The study found that BRCA1 and BRCA2 mutations were present in 2.5% and 3.7% of breast cancer patients, respectively, while PALB2 mutations were present in 0.6% of then." (PMID 38098088, 2023). "They uncovered that the PALB2 mutation female carriers have an eight to nine-fold risk of breast cancer compared with the general population in 2014 August." (PMID 37476378, 2023). "The PALB2 gene is a breast cancer (BC) and ovarian cancer (OC) predisposition gene involved in the homologous recombination repair pathway." (PMID 37169825, 2023). "Recently, PALB2 has been identified as one of the common predisposing genes for breast cancer after BRCA1/2 with penetrance estimated at 33–70% depending on age at diagnosis and family history." (PMID 37169825, 2023). "Germline pathogenic variation in PALB2 disrupts DNA damage repair and increases the risk of Fanconi Anemia, breast cancer, and ovarian cancer." (PMID 37511102, 2023).
breast cancer (continued). "Heterozygous germline PALB2 mutations are associated with an increased risk for breast cancer, with previous studies reporting a higher penetrance in younger than older women." (PMID 36980802, 2023). "The variant p.Ile1035Val in PALB2, associated with breast and ovarian cancers, was identified in two out of eight individuals with breast cancers and in one ovarian cancer person from the extended cohort." (PMID 36845707, 2023). "Heterozygous mutations in the PALB2 gene have been previously linked to susceptibilities to breast cancer (OMIM#114480) and GC." (PMID 37623222, 2023). "Among young breast cancer patients, we detected P/LP PALB2 variants in 1.5% (3/191), similar to studies by Cao (1.3%) and Sluiter (2%)." (PMID 37686625, 2023). "Pathogenic/likely pathogenic PALB2 variants is associated with high risk for breast cancer, with studies showing a life-time risk of 40-60%." (PMID 37781190, 2023). "Currently, there is little risk of familial breast cancer development in patients with mutations in the PALB2 gene." (PMID 37628606, 2023). "Overall, studies suggest that patients with breast cancer harbor P/LP PALB2 variants in 0.4–3% of the cases; however, it is also suggested that the prevalence strongly varies in different populations." (PMID 37686625, 2023). "Here we report a possible association of PALB2 PTVs with high risk of breast cancer overall (p = 0.06) and ER-negative disease (p < 0.05)." (PMID 37790698, 2023). "The estimated risk of P/LP PALB2 variants for female breast cancer was determined as 53%, while only a modestly increased risk for ovarian cancer was implied (4.8% to age 80)." (PMID 37686625, 2023). "PALB2 P/LP variants represent an increased risk for female breast cancer that falls between the classic “high” and “moderate” categories." (PMID 37686625, 2023). "New guidelines for PALB2 mutation in breast cancer advise pancreatic cancer screening, which includes M.R.I.s of the pancreas as well as endoscopic ultrasonography, for women who have a family history of pancreatic cancer." (PMID 35779338, 2022). "Pathogenic PALB2 variants confer an estimated 5.3-fold increase in breast cancer risk in women (95% CI: 1.8–13.2)." (PMID 35454911, 2022). "The responses of patients with breast cancer were driven, in part, by patients with germline mutations in PALB2(gPALB2; encoding partner and localizer of BRCA2) and were correlated with high HRD scores." (PMID 36253484, 2022). "In our work, the PALB2 gene choice as a “demonstrator gene” is based on the fact that this gene is methylated or mutated in different types of cancer including breast cancer." (PMID 36278678, 2022). "Protein truncating variants in ATM, BRCA1, BRCA2, CHEK2, and PALB2 are associated with increased breast cancer risk, but risks associated with missense variants in these genes are uncertain." (PMID 35585550, 2022). "According to a study of 524 families with germline PALB2 mutations, the risk of pancreatic cancer was estimated to be 2–3% by age 80, compared to an estimated 53% risk of breast cancer in women." (PMID 35163129, 2022). "For women who have a family history of pancreatic cancer, new guidelines for PALB2 mutation in breast cancer advise pancreatic cancer screening, which includes M.R.I.s of the pancreas as well as endoscopic ultrasonography." (PMID 35779338, 2022). "But the prevalence rate of PALB2 mutations in a non-BRCA1/2 breast cancer population specifically selected for a family history of pancreatic cancer did not appear to be significantly increased compared to that observed in other breast cancer populations." (PMID 35779338, 2022). "PALB2 loss-of-function variants are associated with significant increased risk of breast cancer as well as other types of tumors." (PMID 36139699, 2022). "Germline mutations in PALB2 have been identified in approximately 1–2% of familial breast cancer cases and 3–4% of HPC cases." (PMID 35761384, 2022).
breast cancer (continued). "Germline mutations of PALB2 increase the risk of pancreatic cancer; although, the risk is lower than that of breast cancer." (PMID 35163129, 2022). "PALB2 mutations has been observed to be a risk factor for early-onset breast cancer in several populations." (PMID 36685821, 2022). "Previous studies suggested that PALB2 served as a potential tumor suppressor gene, and its mutation led to increased susceptibility to breast cancer." (PMID 36158641, 2022). "As heterozygous disruption of Becn1 delays Palb2-associated mammary tumor development, we sought to further examine the role of autophagy in mammary tumor development following PALB2 loss." (PMID 35404932, 2022). "The mutation of PALB2 is mainly reported to influence DNA homologous recombination repair in other tumors, especially breast cancer." (PMID 36158641, 2022). "PALB2 (1.2%) was the most commonly mutated gene other than BRCA1/2 in Chinese breast cancer patients, while CHEK2 (2.82%), ATM (1.06%), and PALB2 (0.87%) were the most commonly mutated genes other than BRCA1/2 in European populations." (PMID 35494038, 2022). "Women with PALB2 mutation have a 40% to 60% higher risk of breast cancer, almost equivalent to women who have BRCA mutations." (PMID 35779338, 2022). "Women with PALB2 mutations have a 40% to 60% higher risk of breast cancer, almost equivalent to women who have BRCA mutations." (PMID 35779338, 2022). "PALB2 is considered a high/moderate breast cancer risk gene, since germline pathogenic variants confer a lifetime risk of developing breast cancer of 53%." (PMID 35456488, 2022). "Biallelic germline loss-of-function mutations in PALB2 cause Fanconi’s anemia, whereas monoallelic loss-of-function mutations are associated with an increased risk of breast cancer." (PMID 35409110, 2022). "Pathogenic germline variants (PGVs) in one of the known high-risk breast cancer susceptibility genes e.g. BRCA1, BRCA2, PALB2 confer a high risk of developing breast cancer and are enriched in familial cases." (PMID 33763779, 2022). "Partner and Localizer of BRCA2 (PALB2), also known as FANCN, is a moderate-risk breast cancer susceptibility gene involved in both to the FA pathway." (PMID 35563100, 2022). "Some studies have also indicated that PALB2-mutated breast cancer is closely correlated with aggressive clinicopathological features, including triple-negative phenotype, advanced disease stage, high Ki67 levels, and poor prognosis." (PMID 35853885, 2022). "In patients with germline PALB2 mutated breast cancers, the ORR was 82%, and the median PFS was 13 months." (PMID 35158866, 2022). "PALB2 is a known breast cancer susceptibility gene with risk of breast cancer estimated to be approximately 14% to age 50 and 53% to age 8085." (PMID 35732815, 2022). "PALB2 loss-of-function variants confer high risk of developing breast cancer (BC) as well as other types of cancers." (PMID 36139699, 2022). "Promoter hypomethylation in PALB2, a breast cancer susceptibility gene that localizes the BRCA2 gene at the site of DNA damage, has been established as a biomarker for sporadic breast cancer." (PMID 34576196, 2021). "Breast cancers associated with PALB2 PGVs tended toward phenotypes seen with a BRCA2 PGV, namely both triple negative and high-grade ER-positive HER2-negative tumors." (PMID 34113003, 2021). "PALB2 is now considered high risk by many because it confers an RR of breast cancer by more than five-fold." (PMID 34573353, 2021). "The identified truncating PALB2 c.1592delT mutation has been identified as a breast cancer susceptibility gene in the Finnish population with a prevalence of 0.2% and a 6-fold increased risk of breast cancer in the general population." (PMID 34084283, 2021). "More importantly, breast cancer patients with known PALB2 mutations are known to have a poor prognosis." (PMID 33420229, 2021). "Our study shows that mutations in the CHEK2 and PALB2 genes are important risk factors for male breast cancer in Poland." (PMID 34461861, 2021).
breast cancer (continued). "It is of interest to document the analysis of non-synonymous SNPs ofPALB2 due to the importance of PALB2 in DNA damage response and its contribution to developing breast cancer risk." (PMID 34092963, 2021). "We have previously reported relatively poor survival for women with breast cancer and a PALB2 mutation." (PMID 34461861, 2021). "The prevalence of the PALB2 mutation in breast cancer varies across different ethnic groups; hence, it is of intense interest to evaluate the cancer risk and clinical association of PALB2 mutation in Chinese breast and/or ovarian cancer patients." (PMID 34439348, 2021). "Another clinical trial (NCT04756765) based on the use of talazoparib on advanced PALB2 mutation associated breast cancer is currently underway." (PMID 34439348, 2021). "PALB2 mutation carriers were more likely have hormonal positive tumors and were likely to have familial aggregation of breast cancer." (PMID 34439348, 2021). "Germline variants in ATM, BRCA1, BRCA2, CHEK2, and PALB2 were associated with a high risk of breast cancer; a more modest risk was associated with BARD1 and RAD51C." (PMID 34445631, 2021). "Considering grade in particular, we also found a marked excess of grade 3 tumors occurring in 76% of all PALB2 PGV associated breast cancers." (PMID 34113003, 2021). "More clinical evidence is needed to demonstrate the effectiveness of PARP inhibitors in patients with PALB2 mutation, and yet breast cancer surveillance is recommended for these mutation carriers." (PMID 34439348, 2021). "They identified an association between mutated PALB2 and female breast cancer (RR = 7.18), male breast cancer (RR = 7.34), ovarian cancer (RR = 2.91), and pancreatic cancer (RR = 2.37)." (PMID 33718150, 2021). "Both of these patients were diagnosed with bilateral breast cancer and both carried a mutation in the PALB2 gene.a- for BRCA1, CHEK2, PALB2, NBN mutation frequencies in cancer-free controls were from our previous studies." (PMID 34461861, 2021). "Pathogenic mutations of PALB2 were found in 39 probands with a mutation frequency of 1.6% and 1% in breast cancer and ovarian cancer patients, respectively." (PMID 34439348, 2021). "The lifetime risk of developing breast cancer in women with the PALB2 mutation is 52.8% by age of 80." (PMID 34439348, 2021). "The only other actionable breast cancer gene consistently identified at a substantial rate is PALB2, which is now considered to be a high-risk gene." (PMID 34439310, 2021). "Subsequently, population-based screenings of PALB2 PVs revealed a 2- to 30-fold increase in the risk of breast cancer." (PMID 33718150, 2021). "In the current study two patients with a PALB2 mutation were diagnosed with bilateral breast cancer and they were diagnosed with the third primary cancer." (PMID 34461861, 2021). "PALB2 is emerging as a gene that confers a high risk of breast cancer, with data suggesting individuals with pathogenic variants in PALB2 have a high lifetime risk of around 32%." (PMID 33917078, 2021).
breast cancer (continued). "In a systematic review of pathogenic PALB2 mutations, 92.5% of cases described were breast cancer patients, 5.0% of cases were ovarian cancer patients, and 2.4% of cases were pancreatic cancer patients." (PMID 34439348, 2021). "Most of the PALB2 mutation carriers had breast cancer (36, 92.3%) and were more likely to have family history of breast cancer (19, 48.7%)." (PMID 34439348, 2021). "Rare protein-truncating variants (PTVs) in PALB2 confer increased risk to breast cancer, but relatively few studies have reported the characteristics of tumours with PALB2 PTVs." (PMID 33893315, 2021). "The prevalence and frequency of the PALB2 mutation in breast cancer varies across different ethnic groups." (PMID 34439348, 2021). "Consistent with its similar molecular functions to BRCA1 and BRCA2, monoallelic germline mutations in PALB2 also confer a high risk of breast cancer and increase the risk of ovarian and pancreatic cancers." (PMID 33893322, 2021). "The prevalence of the PALB2 mutation in breast cancer varies across different ethnic groups; hence, it is of intense interest to evaluate the cancer risk and clinical association of the PALB2 mutation in Chinese breast and/or ovarian cancer patients." (PMID 34439348, 2021). "Breast cancer risk due to loss-of-function variants of PALB2 overlapped with that of BRCA2 variants, validating the direct interaction of PALB2 with BRCA2." (PMID 35008774, 2021). "The PALB2 frameshift mutations included a c.1592delT founder truncation mutation that has been previously identified as a breast cancer susceptibility gene in the Finnish population." (PMID 34084283, 2021). "Recently, there was a report of a PALB2 mutation-carrying breast cancer patient treated with carboplatin for 7 months, whom after relapse showed complete response and disease-free post 30-months of treatment." (PMID 34439348, 2021). "Mutations in PALB2 have been reported in breast cancer, Fanconi anemia subtype FA-D1, and pancreatic cancer." (PMID 34549727, 2021). "Evidence supports that the PALB2 mutation confers moderate to high breast cancer risk and increased risk for ovarian and pancreatic cancer." (PMID 34439348, 2021). "Overall, PALB2 mutation carriers with breast cancer had a poor 10-year survival rate of 48% with tumors <2cm, while it dropped to 32% for tumors > 2 cm in diameter." (PMID 34439348, 2021). "Further studies evaluating cisplatin plus everolimus in cohorts with PI3K pathway alteration or PALB2 germline mutation is needed especially in poor prognosis metaplastic breast cancer patients." (PMID 33420229, 2021). "Our study is the first that evaluated the frequency of mutations in the PALB2 gene in men with breast cancer from Poland, which is populated by ethnic Slavs." (PMID 34461861, 2021). "Several studies including breast cancer patients from Russia,Germany and northwest region of China have been identified with PALB2 mutations." (PMID 34092963, 2021). "Other FA genes, such as FANCJ/BRIP1 and FANCN/PALB2, have also been identified as breast cancer susceptibility genes." (PMID 34830134, 2021). "Germline alterations of the PALB2 gene have recently been associated with a high risk of developing breast cancer." (PMID 33718150, 2021). "Mutations of several residues in the MRG-binding region of PALB2 were found in breast cancer patients, including Asp616His, Pro615Ser and Pro621Thr mutations." (PMID 34946951, 2021).